RNY4 (RNA, Ro60-associated Y4)
Synonyms: hY4; Y4
Gene: Miscellaneous RNA gene on chromosome 7 (148,963,315 to 148,963,410, forward strand). Ensembl gene ENSG00000252316.
Homologues: Orthologues: chimpanzee Y_RNA (100% identical), macaque Y_RNA (100% identical), rabbit RNY4 (100% identical), dog Y_RNA (99% identical), pig Y_RNA (98% identical). Paralogues in human: RNY4P6 (96% identical), RNY4P7 (93% identical), RNY4P10 (92% identical), RNY4P13 (92% identical), RNY4P17 (92% identical), RNY4P3 (92% identical), Y_RNA (92% identical), RNY4P14 (91% identical), RNY4P19 (91% identical), RNY4P23 (91% identical), RNY4P25 (91% identical), Y_RNA (91% identical), and 90 more.
Diseases named in the same sentence as RNY4 in open-access papers:
RNY4 is named in the same sentence as 29 diseases in open-access papers, as found by Europe PMC text mining. Sharing a sentence is not in itself a finding about the gene and the disease. The quoted sentences say what the papers report.
bladder cancer (2 papers, 2023 to 2024). "These Y RNAs (RNY1, RNY3, RNY4, and RNY5) are reportedly similarly downregulated in human bladder cancer versus normal urothelial bladder tissue and act as a prognostic indicator for this condition." (PMID 37835660, 2023). "Overall, the downregulated hypoxia-related Y RNA expression trend in COM is consistent with the expression level of Y RNAs (RNY1, RNY3, RNY4, RNY5) in human melanoma, prostate, and urinary bladder cancer, and appears to distinguish the metastatic and non-metastatic melanoma." (PMID 38288969, 2024).
benign prostate hyperplasia (1 paper, 2023). "Oncologists focusing on the human prostate have found that RNY1, RNY3, RNY4, and RNY5 are downregulated in prostate adenocarcinoma versus normal tissue and benign prostate hyperplasia." (PMID 37835660, 2023).
lymph node metastasis (1 paper, 2017). "RNY1, RNY3 and RNY4 expression was associated with advanced stage (muscle invasive BCA, lymph node metastasis) and grade (G3 tumors when opposed to G1 and G2)." (PMID 29126388, 2017). "Presence of lymph node metastases was also associated with decreased RNY1 (p < 0.001), RNY3 (p < 0.001) and RNY4 (p = 0.007) expression." (PMID 29126388, 2017). "A low expression of RNY1, RNY3 and RNY4 was associated with muscle-invasive BCA, lymph node metastases and advanced grade." (PMID 29126388, 2017).
mastitis (1 paper, 2013). Inflammation of breast tissue during lactation or postpartum due to an obstructed duct or infection. "We have found that this Y RNA gene is 99% identical to human Y RNA 4 (RNY4) and was expressed but not differentially expressed in BME cells infected with a mastitis causing pathogens." (PMID 24223582, 2013).
measles (1 paper, 2025). A highly contagious viral infection caused by the measles virus. "In particular, increased expression of RNY4 has been observed in dengue virus, measles, and HIV-1 infections." (PMID 40510596, 2025).
non-Hodgkin lymphoma (1 paper, 2023). Distinct from Hodgkin lymphoma both morphologically and biologically, non-Hodgkin lymphoma (NHL) is characterized by the absence of Reed-Sternberg cells, can occur at any age, and usually presents as a localized or generalized lymphadenopathy associated with fever and weight loss. "RNY4 fragments are highly abundant in non-Hodgkin lymphoma-derived EVs." (PMID 37835660, 2023).
urothelial carcinoma (1 paper, 2017). A malignant neoplasm derived from the transitional epithelium of the urinary tract (urinary bladder, ureter, urethra, or renal pelvis). "The expression of all four YRNAs (RNY1, RNY3, RNY4, RNY5) was determined in archival BCA (urothelial carcinoma, n = 88) and normal urothelial bladder (n = 30) tissues using quantitative real-time PCR." (PMID 29126388, 2017).
tumor (12 papers, 2008 to 2026). "As expected, more RNY4 copies were detected by the less selective method than by protocols that enrich tumor-derived material before extraction." (PMID 32455948, 2020). "RNY1, RNY3 and RNY4 show good discriminative ability between tumor and normal tissue, as well as between muscle-invasive and non-muscle-invasive urothelial carcinoma." (PMID 29126388, 2017). "Indeed, the advantage of tumor exosome enrichment for the detection of AR-V7 is appreciated when normalized values (AR-V7 vs. RNY4) or AR-V7 allelic frequency are compared." (PMID 32455948, 2020). "In our study we were able for the first time to show that RNY1, RNY3 and RNY4 could very good discriminate between the normal and tumor tissue with a maximal AUC of 0.863 (RNY3), and to a lesser extent between muscle-invasive and not-muscle-invasive tumors (maximal AUC 0.780 for RNY3)." (PMID 29126388, 2017).
cancer (6 papers, 2017 to 2024). A tumor composed of atypical neoplastic, often pleomorphic cells that invade other tissues. "The increased levels of RNY4-derived fragments or full-length transcripts circulating in plasma or exosomes of cancer patients compared to HD triggered interest in the potential use of RNY4 as a cancer biomarker." (PMID 32175280, 2020). "Expression of YRNA was significantly correlated with BCA patients’ overall (RNY1, RNY3, RNY4) and cancer-specific (RNY1, RNY3) survival (all log rank p < 0.05)." (PMID 29126388, 2017). "Furthermore, expression of RNY1 and RNY3 was predictive for BCA patients’ overall (also RNY4) and cancer-specific survival as estimated using Kaplan-Meier and univariate (but not multivariate) Cox regression analyses." (PMID 29126388, 2017). "As the here identified candidates VTRNA1-1, RNY1, and RNY4 have been suggested to distinguish cancer from normal counterparts, and VTRNA1-1 also to inhibit apoptosis and affect chemoresistance, they could have roles in the mechanisms that are involved also in the aggressiveness of TNBC." (PMID 36585466, 2022). "C. ATAC-seq values for of human vtRNA3-1P, vtRNA2-2P and RNYs (RNY1, RNY3, RNY4 and RNY5) in 21 different tumors with at least 5 tumor samples available in Pan-Cancer TCGA dataset (385 tumors samples) expressed as log2 normalized values." (PMID 34354812, 2021). "The distribution of ATAC-seq values for of human vtRNA3-1P, vtRNA2-2P and RNYs (RNY1, RNY3, RNY4 and RNY5) in Pan-Cancer TCGA dataset (385 tumors samples across 23 cancer types) expressed as log2 normalized values." (PMID 34354812, 2021). "Importantly, the expression levels of RNY1 and RNY3 were significantly predictive for cancer-specific and overall survival of BCA patients with a clear trend for RNY4." (PMID 29126388, 2017).
infection (2 papers, 2020 to 2023). The state of being infected such as from the introduction of a foreign agent such as serum, vaccine, antigenic substance or organism. "Surprisingly, despite the widespread infection with the virus, changes in the transcriptome remained limited to only a few genes: GALR3, EGR1, E2F2, RNY4, DBX2 were found upregulated, and ITM2C was downregulated." (PMID 33490061, 2020).
RNY4 also shares sentences with these, for which no sentence is quoted: chronic lymphocytic leukemia (5 papers); lung carcinoma (3); clear cell renal cell carcinoma (2); acute coronary syndrome (1); acute lymphoblastic leukemia (1); anaplastic large cell lymphoma (1); breast carcinoma (1); cervical cancer (1); colon cancer (1); glioma (1); influenza infection (1); kidney tumours (1); malaria (1); melanoma (1); multiple myeloma (1); pancreatic ductal adenocarcinoma (1); prostate adenocarcinoma (1); prostate tumours (1); small cell lung carcinoma (1).